PLPP5 (phospholipid phosphatase 5)
Description:
Magnesium-independent phospholipid phosphatase with broad substrate specificity. Preferentially catalyzes the conversion of diacylglycerol pyrophosphate into phosphatidate but can also act on phosphatidate and lysophosphatidate. Phospholipid phosphatases are involved in both the synthesis of lipids and the generation or degradation of lipid-signaling molecules.
Synonyms: DPPL1; HTPAP; PPAPDC1B
Tractability: Antibody: UniProt places it where antibodies can reach, with high confidence; its Gene Ontology location is reachable by antibodies, with high confidence; UniProt predicts a signal peptide or a membrane-spanning region. PROTAC: ubiquitination databases record sites on it.
Gene: Protein-coding gene on chromosome 8 (38,263,130 to 38,269,243, reverse strand). Ensembl gene ENSG00000147535.
Subcellular location: Cell membrane
Subcellular location (Human Protein Atlas): Vesicles
Pathways (Reactome):
Immune System: Role of phospholipids in phagocytosis
Gene Ontology:
Molecular function: diacylglycerol diphosphate phosphatase activity; phosphatidate phosphatase activity; protein binding; lysophosphatidic acid phosphatase activity
Biological process: phospholipid dephosphorylation; phospholipid metabolic process
Cellular component: cytoplasm; membrane; plasma membrane
Genetic constraint (gnomAD): Loss-of-function variants: 30 observed, 21.7 expected, observed/expected ratio (o/e) 1.38, 90% interval 1.03 to 1.83. The upper end of that interval is the gene's LOEUF score, 1.83, which puts it in group 6 of 6, group 1 being the genes least tolerant of losing a copy. Missense variants: 315 observed, 305.82 expected, observed/expected ratio (o/e) 1.03, 90% interval 0.94 to 1.13. Synonymous variants: 143 observed, 119.63 expected, observed/expected ratio (o/e) 1.2, 90% interval 1.04 to 1.37.
Homologues: Orthologues: chimpanzee PLPP5 (100% identical), macaque PLPP5 (99% identical), pig PLPP5 (87% identical), dog PLPP5 (86% identical), mouse Plpp5 (85% identical), rat Plpp5 (70% identical), guinea pig PLPP5 (66% identical), zebrafish plpp5 (59% identical), Drosophila melanogaster CG12746 (42% identical), Drosophila melanogaster wun2 (23% identical), Drosophila melanogaster wun (23% identical), Drosophila melanogaster CG11426 (22% identical), and 4 more. Paralogues in human: PLPP4 (58% identical), PLPP2 (25% identical), PLPP3 (25% identical), PLPPR4 (24% identical), PLPP1 (23% identical), PLPPR3 (23% identical), PLPPR1 (20% identical), PLPPR2 (20% identical), PLPPR5 (17% identical).
Diseases named in the same sentence as PLPP5 in open-access papers:
PLPP5 is named in the same sentence as 13 diseases in open-access papers, as found by Europe PMC text mining. Sharing a sentence is not in itself a finding about the gene and the disease. The quoted sentences say what the papers report.
breast carcinoma (6 papers, 2010 to 2023). "PLPP5 is estimated to be amplified in 10–15% of ductal breast carcinomas, and its knock-down in breast cancer cell lines causes an increase in apoptosis." (PMID 30042348, 2018). "However, in breast cancer cell lines, down-regulation of PLPP5 inhibits tumor growth and increases apoptosis, which is consistent with our study." (PMID 38111587, 2023). "Frequently affected genes by CNVs in Chinese breast cancer patients were ERBB2 (25%), MIEN1 (25%), GRB7 (24%), TRPS1 (6%), MYC (6%), ERLIN2 (6%), PLPP5 (6%), NSD3 (6%), FGFR1 (6%), and CCND1 (5%)." (PMID 33173047, 2020). "Although the function of PLPP5 has not been determined, it has been proposed to have an oncogenic role in breast cancer." (PMID 30042348, 2018).
lung carcinoma (3 papers, 2016 to 2025). "PLPP5 encodes a phosphatase which is frequently amplified in epithelial cancers, including breast, pancreatic, and lung cancers." (PMID 40242904, 2025).
hepatocellular carcinoma (2 papers, 2014 to 2018). A malignant tumor that arises from hepatocytes. "PLPP5 (also known as PPAPDC1B and HTPAP) encodes a lipid phosphatase that has been shown to be present on the plasma membrane and within the cytoplasm of PLPP5 overexpressing human hepatocellular carcinoma cell lines." (PMID 30042348, 2018).
anemia (1 paper, 2025). A reduction in the number of red blood cells, the amount of hemoglobin, and/or the volume of packed red blood cells.
Autoimmunity (1 paper, 2018). The occurrence of an immune reaction against the organism's own cells or tissues. "As B cell depletion using Rituximab has been successfully used for many years in lymphoma and some autoimmune contexts, the expression of PLPP5 in B cells is not likely to be an insurmountable obstacle for an anti-PLPP5-based therapy for MM or Ab mediated autoimmunity." (PMID 30042348, 2018).
Multiple Myeloma (1 paper, 2018). "The expression of PLPP5, CLPTM1L and ITM2C varied between different established human myeloma cell lines, however, all cell lines examined had detectable expression of at least one of these genes of interest." (PMID 30042348, 2018).
small cell lung carcinoma (1 paper, 2023). Small cell lung cancer (SCLC) is a highly aggressive malignant neoplasm, accounting for 10-15% of lung cancer cases, characterized byrapid growth, and early metastasis. "PLPP5 participates in the regulation of many cancer-associated transduction pathways such as the JAK/STAT, and its overexpression in pancreatic and small cell lung cancer cells may promote proliferation and survival." (PMID 38111587, 2023).
cancer (7 papers, 2014 to 2023). A tumor composed of atypical neoplastic, often pleomorphic cells that invade other tissues. "Moreover, PLPP5 was found in several cancers, including breast cancer, pancreatic adenocarcinoma, and lung carcinoma." (PMID 34917513, 2021). "PLPP5, CLPTM1L and ITM2C are poorly characterized proteins, whose functions are unknown, although mutation in CLPTM1L has been associated with several human cancers (see Discussion)." (PMID 30042348, 2018).
tumor (7 papers, 2010 to 2025). "The amplification and overexpression of PLPP5 are linked to enhanced tumor survival and growth." (PMID 40242904, 2025). "PLPP5 is considered a key driver of tumor cell survival and transformation." (PMID 40242904, 2025). "PLPP5 (phospholipid phosphatase 5, or HTPAP) was defined as a metastatic suppressor of HCC, which was down-regulated in tumor samples." (PMID 33043022, 2020).
PLPP5 also shares sentences with these, for which no sentence is quoted: lung adenocarcinoma (1 paper); lung squamous cell carcinoma (1); lymphoma (1); rectal adenocarcinoma (1).